MAFA (MAF bZIP transcription factor A)
Description:
Transcription factor that activates insulin gene expression. Acts synergistically with NEUROD1/BETA2 and PDX1. Binds the insulin enhancer C1/RIPE3b element. Binds to consensus TRE-type MARE 5'-TGCTGACTCAGCA-3' DNA sequence.
Synonyms: RIPE3b1; hMafA; INSDM
Tractability: PROTAC: UniProt records ubiquitination sites on it.
Gene: Protein-coding gene on chromosome 8 (143,419,182 to 143,430,732, reverse strand). Ensembl gene ENSG00000182759.
Subcellular location: Nucleus
Pathways (Reactome):
Developmental Biology: Regulation of gene expression in beta cells
Gene Ontology:
Molecular function: DNA binding; DNA-binding transcription factor activity; sequence-specific double-stranded DNA binding; DNA-binding transcription factor activity, RNA polymerase II-specific; RNA polymerase II cis-regulatory region sequence-specific DNA binding; DNA-binding transcription activator activity, RNA polymerase II-specific
Biological process: insulin secretion; positive regulation of transcription by RNA polymerase II; response to glucose; regulation of DNA-templated transcription; regulation of transcription by RNA polymerase II
Cellular component: nucleus; chromatin
Genetic constraint (gnomAD): Missense variants: 544 observed, 329.94 expected, observed/expected ratio (o/e) 1.65, 90% interval 1.54 to 1.77. Synonymous variants: 241 observed, 152.02 expected, observed/expected ratio (o/e) 1.59, 90% interval 1.43 to 1.76.
Homologues: Orthologues: chimpanzee MAFA (97% identical), macaque MAFA (97% identical), mouse Mafa (95% identical), pig MAFA (95% identical), rat Mafa (94% identical), dog MAFA (89% identical), guinea pig MAFA (83% identical), tropical clawed frog mafa (64% identical), zebrafish mafaa (63% identical), Drosophila melanogaster tj (33% identical), Caenorhabditis elegans maf-1 (14% identical), Drosophila melanogaster maf-S (14% identical). Paralogues in human: MAF (54% identical), MAFB (54% identical), NRL (36% identical), MAFK (19% identical), MAFG (18% identical), MAFF (17% identical).
Diseases named in the same sentence as MAFA in open-access papers:
MAFA is named in the same sentence as 30 diseases in open-access papers, as found by Europe PMC text mining. Sharing a sentence is not in itself a finding about the gene and the disease. The quoted sentences say what the papers report.
diabetes (57 papers, 2011 to 2025). "In conclusion, it is likely that down-regulation of MafA expression is closely associated with β-cell failure found in type 2 diabetes mellitus." (PMID 35453568, 2022). "The loss of MafA in β-cell leads to a deeper loss of cell identity, which is implicated in diabetes pathology." (PMID 34638652, 2021). "MafA-deficient mice showed symptoms of diabetes mellitus and islet cells of type II diabetes (T2D) patients expressed MafA at a low level." (PMID 32824212, 2020). "TG mice had impaired glucose tolerance and some of them indeed developed diabetes due to the reduction of β cell mass, which is associated with decreased Pdx1 and MafA in β cells." (PMID 22384192, 2012). "In adult mice, loss or dysfunction of MafA impairs the ability of β cells to maintain their mature phenotype, resulting in a reduced β cell/α cell ratio, impaired insulin production, and β cell failure in diabetes." (PMID 40906536, 2025). "A missense mutation of MAFA (p.Ser64Phe, c.191C > T) induces the phenotypes of both insulinomatosis and diabetes; in addition, the mutation was found to decrease phosphorylation within the transactivation region of MAFA, similar to a mutation of c-MAF on a GSK3 phosphorylation site." (PMID 37895232, 2023). "MafA-deficient mice show glucose intolerance and develop diabetes." (PMID 35656076, 2022). "Reduced MafA expression is associated with diabetes progression in mice and human patients." (PMID 35454124, 2022). "However, the MafA deficient mice developed diabetes postnatally, suggesting that MafA regulates maturation and is required for glucose-responsive expression of insulin in adult β cells." (PMID 34882233, 2021). "Interestingly, the fasting blood glucose concentration was sustained at a normal level as a control in this study, while we found in our previous study that MafA-deficient mice developed diabetes because of hyperglycemia." (PMID 31208980, 2019). "Notably, the decrease of insulin+MafA+ cells and the increase of insulin+MafB+ cells preceded the onset of diabetes, consistent with a causative role in hyperglycaemia, rather than a consequence thereof." (PMID 28598424, 2017). "Interestingly, ONECUT1, a genetic risk gene for monogenic recessive diabetes, has been shown to directly repress expression of MAFA, the key regulator of insulin expression in β‐cells, suggesting that the regulatory network that underlies insulin control in vivo is maintained on‐chip." (PMID 36285680, 2022). "Here comes an important question: How can we justify the increase in PDX and MafA levels in controlling diabetes?" (PMID 39238175, 2024). "It has been shown that the loss of MafA is an early indicator of β-cell inactivity due to hyperglycaemia, which precedes the reduction in PDX-1 and NeuroD1 for the development of diabetes." (PMID 38745946, 2024). "In response, levels of MafA and other β-cell functional markers are further reduced by β-cell dysfunction and inflammatory stress, which then leads to a vicious cycle with diabetes progression eventually." (PMID 38027145, 2023). "It is likely that reduced expression levels of MafA and PDX-1 and/or incretin receptor in β-cells are closely associated with β-cell failure in type 2 diabetes mellitus." (PMID 35453568, 2022). "These proteins can function as antioxidants to repair molecules that are oxidized by reactive oxidative intermediates, which can preserve the expression of MAFA and insulin, and improve β-cell function in diabetes mouse models." (PMID 35562869, 2022). "Numerous studies have demonstrated that the expression of MAFA is impaired in β-cells of rodents and humans with diabetes." (PMID 35562869, 2022). "The protein stability of MAFA is regulated by its phosphorylation, which is also involved in β-cell dysfunction in diabetes." (PMID 35562869, 2022).
diabetes (continued). "The importance of MafA for glucose homeostasis was shown in MafA-deficient mice, which displayed glucose intolerance after weaning due to impaired glucose-stimulated insulin secretion (GSIS) and age-dependent diabetes progression." (PMID 35454124, 2022). "In mRNA expression levels in isolated islets, insulin and its transcriptional factors such as Pdx-1 and MafA were significantly increased in combination therapy in an early phase of diabetes." (PMID 34373487, 2021). "Knockout mice for MafA develop glucose intolerance and diabetes, lower expression of the insulin gene, PDX-1, NeuroD and GLUT2." (PMID 34638652, 2021). "The expression of MafA gene is down-regulated, thus inhibiting the transcription of insulin in diabetes mellitus." (PMID 32038500, 2020). "In MafA knockout mice, insulin biosynthesis and secretion are reduced, leading to diabetes mellitus, indicating the importance of MafA in β-cells." (PMID 33322512, 2020). "We also showed that the human β-cell-specific gene DLK1 was significantly positively correlated with both MAFA and MAFB which had also been implicated in the progression of diabetes by impairing β-cell function." (PMID 30567413, 2018). "Also the transcription factor MafA is critical for maintenance of the mature beta cell phenotype in mice and deletion of MafA resulted in reduced beta to alpha cell ratio and upregulation of disallowed islet genes leading to dedifferentiation of beta cells, which is implicated in diabetes." (PMID 28792951, 2017). "Reprogramming acinar cells into insulin producing cells using adenoviral (Ad)-mediated delivery of Pdx1, Ngn3 and MafA (PNM) is an innovative approach for the treatment of diabetes." (PMID 26690959, 2015). "It has recently been shown that under diabetes-related stress, the expression and activity of key β cell transcription factors, including MafA, Nkx6.1, and Pdx1, are compromised." (PMID 25233132, 2014). "We also checked the genes RNF128 and MAFA, which were ranked at top 1 and top 2 for diabetes, respectively." (PMID 24344781, 2013). "In the present study, we provide evidence that PDAC-associated diabetes is distinguished by a global downregulation of key islet hormones (INS, GCG) as well as β-cell-enriched transcription factors such as MAFA and PAX4, and hormone receptors such as GCGR, SSTR3 and SSTR5." (PMID 40244011, 2025). "Also, other miRNAs are involved in diabetes by modulating key TFs, such as miR-204-5p, which downregulates MafA expression, and miR-372-3p, which targets growth factor-16." (PMID 38916841, 2024). "The regulation of TXNIP, miR-204, and MafA might play an important role in the mechanism of diabetes remission following bariatric surgery." (PMID 36733403, 2023). "The expression of MAFA in β-cells is impaired in humans with diabetes." (PMID 35562869, 2022). "Indeed, the expression of MAFA induced by a Cre-loxP-Rosa system in β-cells of diabetes model mice increased plasma insulin, ameliorated elevated blood glucose and HbA1c, and preserved β-cell function." (PMID 35562869, 2022). "Here, PDX-1 and MafA were markedly downregulated following diabetes establishment in rats." (PMID 35656076, 2022). "In addition to c-JUN, which is induced by oxidative stress, another important factor that can deteriorate β-cell function via the downregulation of MAFA during diabetes is TXNIP, a cellular redox regulator." (PMID 35562869, 2022). "Moreover, it was clearly demonstrated that MafA overexpression in β-cells preserved β-cell mass and function and finally alleviated β-cell failure, which is often observed in type 2 diabetes mellitus." (PMID 35453568, 2022). "Inducing MAFA expression in individuals with diabetes could maintain the mature and functional β-cells." (PMID 35562869, 2022). "Further elucidation of the molecular underpinnings of MafA regulation may provide novel therapeutic targets for the treatment and prevention of diabetes." (PMID 35454124, 2022).
diabetes (continued). "For instance, MafA was first identified as the trans-acting factor binding the RIPE3b/C1 element of the insulin promoter and has since been characterized as an important TF for β-cell function that is dysregulated in diabetes progression." (PMID 35454124, 2022). "Previous studies reported that MAFA was a transcription factor binding RIPE3b, a conserved enhancer element that regulated pancreatic beta cell-specific expression of the insulin gene, which was involved in Insulinomatosis and Diabetes Mellitus." (PMID 32680461, 2020). "The overexpression of PDX1 and MafA successfully reprogrammed alpha-cells into beta-cells in vitro and in vivo, providing a significant restoration of islet function and delaying the onset of diabetes." (PMID 32708678, 2020). "MafA, an efficacious activator of insulin gene transcription, may be a novel target for the treatment of diabetes." (PMID 30337946, 2018). "Take a step further to determine whether the induced IPCs give full scope to normal physiological functions of β islet cells, mMSCs expressing a combination of PDX-1, NeuroD1, and MafA were transplanted into the livers of mice with STZ-induced diabetes." (PMID 22761608, 2012). "It is therefore possible that with age individuals who develop diabetes could have some disruption in MafA levels as it is already known that in diabetes, MafA levels are reduced." (PMID 21765202, 2011). "Thus, a decreased nuclear expression of MafA could lead to a beta cell dysfunction and, eventually, a progression towards diabetes." (PMID 38745946, 2024). "In MafA-/- mice, insulin 1, insulin 2, PDX-1, neurogenic differentiation (NeuroD) and glucose transporter 2 (GLUT2) amounts are reduced, and glucose, arginine and KCl-induced insulin secretion are remarkably altered Thus, PDX-1 and MafA may be important factors in diabetes therapy." (PMID 35656076, 2022). "The link between MAFA expression and GSIS development, and, further, between MAFA expression and the maturity of beta cells, is supported by studies in MAFA-deficient mice, which demonstrate impaired GSIS, abnormal architecture of islets, and overt diabetes by postnatal 50 weeks." (PMID 29096722, 2017). "MAF BZIP Transcription Factor A (MAFA), Neuronal Differentiation 1 (NEUROD1) and NEUROD4 were significantly downregulated (p < 0.05) in the diabetes cohort, suggesting a disruption in the transcriptional regulation of β-cell identity and function." (PMID 40244011, 2025). "The identification of small molecules to stimulate MAFA expression or function may be useful for the maintenance of normal β-cells or improvement of compromised β-cells and thus would be beneficial for the development of novel strategies for the treatment of diabetes." (PMID 35562869, 2022). "TXNIP is upregulated in β-cells during diabetes and has been shown to induce miR-204 by the inhibition of STAT3 phosphorylation, which in turn directly inhibits MAFA and insulin expression." (PMID 35562869, 2022). "Future studies on the interplays among HMGA1, PDX-1, and MafA might be useful in understanding the molecular basis of clinical phenotypes in certain clinical conditions where insulin secretion becomes compromised (i.e., diabetes mellitus and other categories of glucose intolerance)." (PMID 25628604, 2014). "PDX1 and MAFA transcription factors have been precisely delivered to pancreatic α-cells using AAV8 vectors, reprogramming them into cells that produce insulin and restoring normal blood glucose levels in rats with diabetes." (PMID 41226304, 2025). "Previous studies have also shown a decrease in the expression of MafA and PDX1 in diabetes." (PMID 39238175, 2024). "However, when MafA levels were “rescued” in db/db mice, GSIS and β-cell mass improved, suggesting that preserving MafA expression in β-cells can still mitigate diabetes progression." (PMID 35454124, 2022).
diabetes (continued). "In this manuscript, we investigated expression patterns of 3 TFs with known changes in islet cell development and diabetes: α cell–specific ARX, β cell–specific MAFA, and MAFB, which is expressed in both α and β cells and has a unique expression profile compared with rodent islets." (PMID 34428183, 2021). "In addition, genes in the mature onset diabetes in young people (hsa04950) pathway (such as HES1, GCK, FOXA3, MAFA, HNF4A, HHEX, and PDX1) were increased in stages II to IV; these genes are related to insulin secretion and the maturation of pancreatic β-cells." (PMID 33897780, 2021). "In this study, we demonstrate that, with the experimental set-up described, insulin+, MAFA+, NKX6.1+ S7 cells can be generated in vitro from hiPSCs regardless of HNF4A mutation carrier status or diabetes status." (PMID 28684784, 2017). "The effect of age on MafA expression levels has not yet been studied, but it has been shown that MafA null mutant mice, though normoglycemic at birth, develop diabetes by four weeks of age." (PMID 21765202, 2011). "MEG3 is downregulated in the islets and blood of individuals with diabetes, and in a murine β-cell line (MIN6), MEG3 seems to regulate insulin synthesis and secretion since its absence reduced the expression of key factors for β-cell function (PDX-1 and MAFA), decreasing insulin synthesis." (PMID 38326874, 2024). "Additionally, it has been shown that such a reduction in insulin biosynthesis and secretion together with a reduction in PDX-1 and MafA is preserved by mitigating pancreatic β-cell failure with insulin preparation or SGLT2 inhibitors, especially in the early stage of diabetes mellitus." (PMID 35453568, 2022). "Additionally, we attempted to dissect the mechanisms by which EGCG mitigated β-cell disturbances, and found that EGCG inhibited experimental diabetes triggered by a high-sucrose-high-fat (HSHF) diet and streptozotocin (STZ) administration by increasing upregulating pancreatic PDX-1 and MafA." (PMID 35656076, 2022). "Most studies have reported reduced expression of MafA and PDX-1 in type 2 diabetes, but no study was found to clarify the effects of N. sativa on MafA and PDX-1 changes in STZ-induced diabetes model (type 1 diabetes)." (PMID 36109786, 2022). "Furthermore, also regardless of HNF4A mutation carrier status or diabetes status, the S7 cells displayed the same GSIS kinetics, the same ultrastructural features and the same levels of proteomics-based protein markers of a mature β-cell, including INS, PDX1, NKX6.1, MAFA, GLUT2, UCN3 and others." (PMID 28684784, 2017).